BAP1 (BRCA1 associated deubiquitinase 1)
Diseases named in the same sentence as BAP1 in open-access papers (continued):
Sharing a sentence is not in itself a finding about the gene and the disease.
mesothelioma (continued). "Also, preclinical reports by us and others have shown that inhibition of EZH2 is therapeutically effective against BAP1-deficient mesothelioma." (PMID 38054839, 2024). "The BAP1 gene was identified and named in 1998 as a powerful tumor suppressor gene, while in 2011 its association with germline and somatic carcinogenesis of mesothelioma was defined." (PMID 38673021, 2024). "BAP1 mutations predispose to uveal melanoma, renal cell carcinoma, and mesothelioma." (PMID 38690732, 2024). "MiST1 enrolled 26 patients with BAP1- or BRCA1-deficient mesotheliomas." (PMID 38610930, 2024). "Positive results could potentially also help in establishing future clinical guidelines for the long-term management of BAP1-tumor predisposition syndrome families, who are at high risk of mesothelioma and other cancers." (PMID 38784478, 2024). "As more than half of patients with mesothelioma have alterations in the gene encoding for BAP1 this could be a potential marker for targeted therapies." (PMID 38054839, 2024). "In addition, the gene encoding the BRCA1-associated protein 1 (BAP1) is found to be mutated, deleted, or epigenetically silenced in multiple cancers with a prevalence of approximately 60% in the mesothelioma patient population." (PMID 38054839, 2024). "Interestingly, the reactive oxygen species and mitochondrial activity were diminished in mesothelioma cells or human fibroblasts, respectively, with the inactivating mutations of the tumor suppressor BAP1." (PMID 38673877, 2024). "Similar to mesothelioma this effect in uveal melanoma is restricted to BAP1-deficient cell lines." (PMID 38054839, 2024). "However, asbestos-unrelated mesothelioma has been diagnosed in young patients carrying germline mutations in BRCA1-associated protein 1 (BAP1) or other tumor suppressor genes." (PMID 39519591, 2024). "Additionally, the presence of BAP1 deletion is a valuable diagnostic confirmation tool for mesothelioma." (PMID 38371337, 2024). "In view of the clinical availability of the inhibitors used against EZH2 (tazemetostat) and FGFR (AZD4547), this highly synergistic combination is worth testing as a therapeutic regimen against mesothelioma and potentially other BAP1-mutated malignancies as well." (PMID 38054839, 2024). "Besides a predisposition for mesothelioma, these patients are also commonly affected by BAP1-inactivated melanocytic tumors, uveal melanoma, cutaneous melanoma and renal cell carcinoma." (PMID 38642130, 2024). "BAP1 is a tumor suppressor gene, and loss of BAP1 nuclear expression, tested by IHC, can be seen in about 70% of epithelioid mesotheliomas, aiding in diagnosis by differentiating between benign mesothelial hyperplasia and mesothelioma." (PMID 39409190, 2024). "Additionally, it has been documented that mesothelioma is causally connected with germline mutations of BRCA1-associated protein 1 (BAP1) and various tumour suppressor genes." (PMID 38671450, 2024). "The inactivation of BAP1 is associated with prolonged survival in patients with mesothelioma." (PMID 39267830, 2024). "In addition to the environmental risk posed by asbestos and other carcinogenic mineral fibers, mesothelioma is associated with genetic risk factors, specifically inherited pathogenic mutations of BAP1 and other genes mainly involved in DNA damage repair." (PMID 38784478, 2024). "Interestingly, we see that the included ATM inhibitor AZD1390, shows high synergistic scores in Bap1-deficient mouse mesothelioma cell lines and in human cell lines almost exclusively in BAP1-deficient cells." (PMID 38519707, 2024). "BAP1 mutations are most prevalent in uveal melanoma, mesothelioma and renal cell carcinoma." (PMID 39554490, 2024). "In line with that hypothesis, in the current study we show that the acute loss of BAP1 in mesothelioma cells leads to the subsequent loss of ATM expression at both mRNA and protein level." (PMID 38519707, 2024).
mesothelioma (continued). "In cohort A (comprising patients with mesothelioma, uveal melanoma, renal cell carcinoma, cholangiocarcinoma), 9 patients demonstrated tumor response (1 partial response, 8 stable disease), out of which 7 had a BAP1 mutation." (PMID 38730642, 2024). "Furthermore, rare BAP1 germline mutations result in the so called ‘BAP1 cancer syndrome’, with a high incidence of uveal melanoma, mesothelioma, and other malignancies." (PMID 38529289, 2024). "The lifetime risk of mesothelioma for BAP1 GPV carriers has been estimated at between 15–25%." (PMID 37607989, 2023). "Two additional mechanisms may account for the association of BAP1 mutations with mesothelioma and its improved survival." (PMID 37880686, 2023). "The availability and use of a reliable, population-based registry of mesothelioma cases made it possible to estimate accurately the etiological role of the BAP1 mutations, which explain the rare syndromic cases of mesothelioma but have a very small role in the sporadic cases." (PMID 36673690, 2023). "Notably, performing gene set enrichment analysis (GSEA) for hallmarks gene sets on our data shows a clear enrichment of the cholesterol homeostasis pathway due to EZH2 inhibition in the BAP1-deficient H2731 mesothelioma cell line." (PMID 36657447, 2023). "In addition, the combined targeting of EZH2 and an enzyme upstream in the mevalonate pathway, i.e., HMG-coenzyme A (CoA) by lovastatin, also results in reduced survival of BAP1-deficient mesothelioma cells." (PMID 36657447, 2023). "We next examined whether the frequent loss of BAP1 in mesothelioma tumours in patients correlates with loss of BRCA1 protein expression." (PMID 36550359, 2023). "Notably, the mutation or deletion of BAP1 are frequently found in melanoma, renal cell carcinoma and mesothelioma which implied a tumor suppressor activity of BAP1." (PMID 37543638, 2023). "BAP1 mutations cause prevalently mesothelioma and melanomas." (PMID 37880686, 2023). "Taken together, these findings suggest that mesothelioma cells with a loss-of-function mutation in Bap1 are dependent on metabolic pathways such as the mevalonate pathway, which may eventually contribute to the pathogenesis of Bap1-deficient mesothelioma." (PMID 36657447, 2023). "Finally, by combined targeting of both vulnerabilities, we demonstrate a potent anti-tumor effect, suggesting a new targeted combination therapy for BAP1-deficient mesothelioma." (PMID 36657447, 2023). "However, we found that BAP1 is likely to control BRCA1 expression at least in part at the level of protein stability in mesothelioma cells, as its loss upon BAP1 depletion was blocked by proteasome inhibition." (PMID 36550359, 2023). "Few individuals in this case series underwent testing for the tumor suppressor gene, BAP-1, which is associated with an increased risk for mesothelioma when associated with asbestos exposure, including greater susceptibility at low doses of asbestos such as exposures from cosmetic talcum powder use." (PMID 36653798, 2023). "In addition to BAP1, recent studies have confirmed an increasing number of candidate genes that predispose patients to developing mesothelioma." (PMID 36833533, 2023). "In addition, Bap1-deficient mesothelioma is dependent on increased Polycomb repression, creating a Bap1-loss-specific vulnerability." (PMID 36657447, 2023). "Another paper, “Germline BAP1 mutations predispose to malignant mesothelioma”, confirmed the existence of a BAP1-associated cancer syndrome characterized by mesothelioma, providing foundations for future studies evidenced by its top-ranking citations and co-citations." (PMID 36833533, 2023). "Overall, our results indicate PRC2-mediated epigenetic silencing could be a driver of the altered transcriptome in BAP1-deficient mesothelioma and may influence upregulation of the mevalonate pathway." (PMID 36657447, 2023).
mesothelioma (continued). "Here, we show that combined targeting of mevalonate pathway and PRC2 dependency convey significant survival benefit in aggressive mouse models of mesothelioma, and thus this combination might be a more viable option for treating BAP1-deficient mesothelioma." (PMID 36657447, 2023). "However, our data show that TG2-179-1 also kills BAP1-deficient mesothelioma and ccRCC cells with significantly strong cytotoxicity." (PMID 36754982, 2023). "We identified a set of 143 genes (absolute log2 fold change > 2 and padj < 0.01) that are significantly deregulated in a manner consistent with chromatin changes in mouse mesothelioma and showing matching gene expression in human mesothelioma due to loss of BAP1 only." (PMID 36657447, 2023). "Up to now, BAP1 is the only gene whose role in determining predisposition to mesothelioma is known." (PMID 37942251, 2023). "In this regard, it may be helpful to design novel therapies that benefit all mesothelioma patients that asbestos-induced mesotheliomas and mesotheliomas developing in carriers of germline BAP1 mutations share at least some of the same pathogenic mechanisms." (PMID 37880686, 2023). "However, some malignancies in germline BAP1 mutation carriers, especially mesotheliomas, are much less aggressive, even if the exact mechanism is not completely understood." (PMID 37626858, 2023). "Inactivating mutations and deletions of the BAP1 gene are found in multiple human cancers, such as mesothelioma, uveal melanoma and renal cell carcinoma, and BAP1 has many anticancer cellular functions, including suppression of cell proliferation and genome instability." (PMID 36754982, 2023). "Interestingly, mesothelioma in patients carrying BAP1 germline mutations is usually diagnosed earlier in life and is much less aggressive than mesotheliomas in the general population." (PMID 36980631, 2023). "In addition, mesothelioma can develop in carriers of germline mutations of BAP1 and of other tumor suppressor genes." (PMID 37880686, 2023). "BAP1 tumour predisposition syndrome (BAP1 TPS) is now recognised as an autosomal dominant condition where individuals carrying heterozygous BAP1 mutations are at high risk of mesothelioma and other cancers including melanoma." (PMID 38015374, 2023). "In order to investigate the impact of BAP1 loss on the epigenome, its consequence on the mesothelioma transcriptome, and the connection with the observed sensitivity to mevalonate pathway, we have studied the BAP1-loss-associated chromatin and expression changes in mouse and human mesothelioma." (PMID 36657447, 2023). "Why are BAP1 inactivating mutations so powerful in causing mesothelioma and other cancers?" (PMID 37880686, 2023). "Therefore, BAP1 mutations activate the same mechanism—HMGB1 nuclear to cytoplasmic to extracellular release—that promotes asbestos-induced mesothelioma." (PMID 37880686, 2023). "On the other hand, BAP1 loss confers a high risk of subsequent appearance of invasive mesothelioma." (PMID 35950141, 2022). "Germline BAP1 mutations have been associated with a hereditary cancer syndrome (the BAP1 tumor predisposition syndrome), characterized by an increased incidence of basal cell carcinoma, renal cell carcinoma, uveal melanoma, mesothelioma, and iCCA." (PMID 36013199, 2022). "Also, for example, mesotheliomas resulting from BAP1 germline mutations are less aggressive than sporadic tumors with a median survival ranging from 5 to 7 years." (PMID 36362209, 2022). "The identification of BAP1 mutation carriers with mesothelioma can be extremely useful because these patients may potentially benefit from precision medicine, as shown for MPM_HO1901." (PMID 35885614, 2022). "BAP1 is mutated in lung cancer, thyroid cancer, kidney cancer, melanoma, and mesothelioma." (PMID 35686121, 2022).
mesothelioma (continued). "Interestingly, type‐1 IFN signaling is associated with the mutational status of BRCA1‐associated protein (BAP1), a tumor suppressor gene often inactivated in mesothelioma, although the underlying mechanisms are not known." (PMID 36221913, 2022). "The finding of BAP1 loss is quite useful in the diagnosis of invasive mesothelioma and MMIS." (PMID 35950141, 2022). "A similar disruption of PcG distal looping may occur through other chromatin modifier-mutated cancers such as BAP1 in mesothelioma, uveal melanoma, and renal clear cell carcinomas." (PMID 36105358, 2022). "Loss of BAP1 in mesothelioma correlates with an inflammatory tumor microenvironment characterized by immune checkpoint receptor activation and BAP1 status might predict ICI therapy benefit." (PMID 36003792, 2022). "In addition, somatic BAP1 mutations are frequent in various human cancers, including uveal melanoma and mesothelioma, and have been noted in breast, lung, and renal cancers 6, but have not previously been appreciated as a significant somatic alteration in HCC." (PMID 34976173, 2022). "Importantly, inherited BAP1 mutations in the form of truncating mutations have been detected in families with members diagnosed with mesothelioma, uveal melanoma, or breast cancer, suggesting a BAP1 familial cancer syndrome due to germline BAP1 mutations." (PMID 33805973, 2021). "BAP1 loss has been consistently reported in approximately 50% of all sporadic mesotheliomas." (PMID 33802313, 2021). "Being a tumor suppressor, loss of BAP1 through germline and somatic mutations has been directly linked to the predisposition of BAP1-mutated individuals to various malignancies including mesothelioma, uveal melanoma, cutaneous melanoma, and clear cell renal cell carcinoma." (PMID 33805973, 2021). "BAP1 loss may play a role in differentiating mesothelioma from carcinoma, with loss in 46/53 (87%) pleural and peritoneal mesotheliomas compared with 4/204 (2%) (p: <0.001) carcinomas in one study." (PMID 34209209, 2021). "In vitro studies suggest that the loss of BAP1 affects the sensitivity of mesothelioma cells to HDACi, indicating that stratification of patients might help to identify a responsive subgroup." (PMID 34226685, 2021). "Importantly, BAP1 restoration in IST-MES2 cells significantly slowed cell growth in a catalytic-dependent manner, demonstrating that mesothelioma tumors remain addicted to the loss of BAP1 activity." (PMID 34186021, 2021). "Moreover, a STOP mutation of BAP1, previously suggested as a candidate predictive biomarker for immunotherapy of mesothelioma, and an emerging therapeutic option, was detected in one biliary ITPN." (PMID 34205964, 2021). "However, in a report by Betti and colleagues, in two out of six families affected by both mesothelioma and melanoma, the authors showed BAP1 germline nonsense mutation or a recurrent pathogenic germline mutation (c.301G > T, pGly101Trp) in the CDKN2A gene." (PMID 33802313, 2021). "Notably, BAP1 loss is uncommon in sarcomatoid and desmoplastic mesothelioma and is demonstrated in other malignancies including melanoma and renal cell carcinoma." (PMID 34209209, 2021). "Other aetiological mechanisms include genetic predisposition, with inherited germline mutations of the BRCA 1-associated protein (BAP1) gene (a tumour suppressor gene involved in modulation of transcription and DNA repair) identified amongst families with high incidence of mesothelioma in 2011." (PMID 34209209, 2021). "Previous studies have suggested that BAP1 functions as a tumor suppressor, and both germline and somatic mutations of BAP1 have been identified in numerous tumor types, including melanoma, mesothelioma, renal cell carcinoma, and breast cancer." (PMID 34830866, 2021). "However, unlike that case, our patient had no family history of cancer, malignant tumors other than lung adenocarcinoma and mesothelioma, and loss of BAP1 expression in lung adenocarcinoma." (PMID 34333253, 2021).
mesothelioma (continued). "Remarkably, however, patients with mesothelioma who carry germline mutations of BAP1 have a significantly better prognosis compared with those with sporadic disease, although the mechanism of this is unknown." (PMID 34226685, 2021). "BAP1 is an important tumor suppressor in human, with somatic or germinal BAP1 mutations being common in mesothelioma, uveal melanoma, renal cell carcinoma, and other cancers, while mutations in BAP1 interacting Polycomb proteins ASXL1/2 are prevalent in myeloid leukemia." (PMID 33912157, 2021). "In fact, while some studies have shown combinatorial treatment with cisplatin and olaparib is effective in mesothelioma cells with a defective HR, another study has demonstrated that olaparib has limited anti-tumor activity also in BAP1 mutated patients (NCT03531840)." (PMID 34249695, 2021). "Inactivating mutations in BAP1 can be found in 23% of mesotheliomas." (PMID 33065998, 2020). "Among the pathogenic variant carriers, cancer spectrum was variable but consistent with BAP1 tumor predisposition syndrome: one presented mesothelioma, two with breast cancers, of whom one also presented multiple cancers including clear cell renal cell carcinoma (ccRCC)." (PMID 33240524, 2020). "BAP1 germline mutations have been also associated with an increased risk of mesothelioma." (PMID 33065998, 2020). "We tried to assess loss of heterozygosity (LOH) by tumor DNA sequencing in both melanomas and mesothelioma tissue; unfortunately, low DNA quality limited our analysis, but immunohistochemistry (IHC) showed loss of BAP1 nuclear expression in the mesothelioma sample." (PMID 32325837, 2020). "BAP1 germline mutations are only present in ~2% of patients with UM but should be considered in the presence of a family history of UM, cutaneous melanoma, mesothelioma, or renal cell carcinoma." (PMID 32718045, 2020). "Loss or mutation of BAP1 gene is a common event in cancer and serves as a potential pathogenetic mechanism in various human malignancies, including uveal melanoma, mesothelioma, small cell and non-small cell lung carcinomas, renal cell carcinoma (RCC), breast cancer, and hepatocellular carcinoma." (PMID 33585209, 2020). "Carriers of inherited loss-of-function mutations in BAP1 are predisposed to mesothelioma." (PMID 32226777, 2020). "In this regard, mesotheliomas in carriers of BAP1 mutations are almost exclusively of the epithelioid type, are well differentiated, and have an overall nonaggressive morphology, consistent with prolonged survival (i.e., oval cells with bland nuclei, rare mitoses, no necrosis)." (PMID 33065998, 2020). "In the present study, significant associations of TC were identified with a cancer family history of cancers related to the BAP1 tumour predisposition syndrome, including mesothelioma, melanoma, squamous cell carcinomas, adenocarcinomas, sarcomas and breast cancer." (PMID 30967648, 2019). "People with one inactive BAP1 allele (BAP1 tumour predisposition syndrome) have a significantly higher predisposition to cancer, and somatic BAP1 point mutations were present in up to 60% of sporadic mesothelioma." (PMID 31766522, 2019). "In addition, in carriers of BAP1 mutations the majority of peritoneal mesothelioma occurs in women, and have a better prognosis, in contrast to sporadic mesotheliomas." (PMID 30001711, 2018). "Relatively low levels of carcinogenic fibers, as those found in areas with environmental exposure, might increase the risk of developing mesothelioma among carriers of germline BAP1 mutations." (PMID 30001711, 2018). "Interestingly, this approach identified already known mesothelioma genes, BAP1 and NF2 being downregulated, and MSLN, which encodes mesothelin, upregulated in MPM in comparison with MH." (PMID 30060470, 2018). "Given that it is estimated that approximately 65% of mesotheliomas harbour mutations inactivating BAP1, this may have implications with respect to the role of this lncRNA in MPM pathogenesis." (PMID 29701689, 2018).